SLC38A3 (solute carrier family 38 member 3)
Description:
Symporter that cotransports specific neutral amino acids and sodium ions, coupled to an H(+) antiporter activity. Mainly participates in the glutamate-GABA-glutamine cycle in brain where it transports L-glutamine from astrocytes in the intercellular space for the replenishment of both neurotransmitters glutamate and gamma-aminobutyric acid (GABA) in neurons and also functions as the major influx transporter in ganglion cells mediating the uptake of glutamine (By similarity). The transport activity is specific for L-glutamine, L-histidine and L-asparagine. The transport is electroneutral coupled to the cotransport of 1 Na(+) and the antiport of 1 H(+) (By similarity). The transport is pH dependent, saturable, Li(+) tolerant and functions in both direction depending on the concentration gradients of its substrates and cotransported ions. Also mediates an amino acid-gated H(+) conductance that is not stoichiometrically coupled to the amino acid transport but which influences the ionic gradients that drive the amino acid transport (By similarity). In addition, may play a role in nitrogen metabolism, amino acid homeostasis, glucose metabolism and renal ammoniagenesis (By similarity).
Synonyms: G17; NAT1; SN1; SNAT3; DEE102
Tractability: Antibody: its Gene Ontology location is reachable by antibodies, with high confidence; UniProt places it where antibodies can reach, with medium confidence; UniProt predicts a signal peptide or a membrane-spanning region. PROTAC: ubiquitination databases record sites on it; its protein half-life has been measured.
Gene: Protein-coding gene on chromosome 3 (50,202,871 to 50,221,504, forward strand). Ensembl gene ENSG00000188338.
Subcellular location: Cell membrane; Basolateral cell membrane
Subcellular location (Human Protein Atlas): Cytosol; Microtubules
Pathways (Reactome):
Transport of small molecules: Amino acid transport across the plasma membrane
Gene Ontology:
Molecular function: L-alanine transmembrane transporter activity; L-asparagine transmembrane transporter activity; L-asparagine, sodium:proton antiporter activity; L-glutamine transmembrane transporter activity; L-glutamine, sodium:proton antiporter activity; L-histidine transmembrane transporter activity; amino acid transmembrane transporter activity; L-histidine, sodium:proton antiporter activity; neutral L-amino acid:sodium symporter activity
Biological process: asparagine transport; glutamine transport; histidine transport; L-alanine transport; amino acid transmembrane transport; amino acid transport; glutamine secretion; intracellular amino acid homeostasis; L-asparagine import across plasma membrane; L-glutamine import across plasma membrane; L-histidine import across plasma membrane; L-histidine transport; transport across blood-brain barrier; asparagine transmembrane transport; female pregnancy; L-histidine transmembrane transport; positive regulation of glutamine transport
Cellular component: plasma membrane; apical plasma membrane; basolateral plasma membrane; membrane
Genetic constraint (gnomAD): Loss-of-function variants: 15 observed, 53.37 expected, observed/expected ratio (o/e) 0.28, 90% interval 0.19 to 0.43. The upper end of that interval is the gene's LOEUF score, 0.43, which puts it in group 1 of 6, group 1 being the genes least tolerant of losing a copy. Missense variants: 451 observed, 654.12 expected, observed/expected ratio (o/e) 0.69, 90% interval 0.64 to 0.75. Synonymous variants: 237 observed, 265.19 expected, observed/expected ratio (o/e) 0.89, 90% interval 0.8 to 1.
Homologues: Orthologues: chimpanzee SLC38A3 (99% identical), macaque SLC38A3 (97% identical), dog SLC38A3 (92% identical), pig SLC38A3 (91% identical), mouse Slc38a3 (90% identical), rat Slc38a3 (90% identical), guinea pig SLC38A3 (89% identical), rabbit SLC38A3 (84% identical), tropical clawed frog slc38a3 (76% identical), zebrafish slc38a3b (69% identical), zebrafish slc38a3a (69% identical), Drosophila melanogaster CG32079 (19% identical), and 12 more. Paralogues in human: SLC38A5 (58% identical), SLC38A4 (54% identical), SLC38A2 (52% identical), SLC38A1 (47% identical), SLC38A6 (42% identical), SLC38A10 (23% identical), SLC38A11 (22% identical), SLC38A9 (21% identical), SLC36A4 (20% identical), SLC38A8 (20% identical), SLC36A1 (19% identical), SLC38A7 (19% identical), and 3 more.
Diseases named in the same sentence as SLC38A3 in open-access papers:
SLC38A3 is named in the same sentence as 42 diseases in open-access papers, as found by Europe PMC text mining. Sharing a sentence is not in itself a finding about the gene and the disease. The quoted sentences say what the papers report.
glioma (5 papers, 2008 to 2023). A benign or malignant brain and spinal cord tumor that arises from glial cells (astrocytes, oligodendrocytes, ependymal cells). "Strong immunoreactivity was revealed for SLC38A3 in high grade gliomas compared to metastases to the brain and control brain tissue." (PMID 27096627, 2016).
breast carcinoma (3 papers, 2021 to 2025). "As a neutral amino acid transporter, SLC38A3 increases the influx of glutamine, asparagine and alanine and enhances the subsequent formation of glutamate and aspartate in breast cancer." (PMID 38785550, 2024). "High levels of SLC38A3 have been shown to increase total β-catenin levels in breast cancer by stabilizing it." (PMID 38785550, 2024). "Another glutamine transporter, SLC38A3, has been reported to promote tumor growth and metastasis in breast cancer and colorectal cancer, implying that SLC38A3 could be a potential therapeutic target in these cancers." (PMID 40552664, 2025). "Lactate levels are reduced in breast cancer cells when SLC38A3 is suppressed." (PMID 38785550, 2024). "SLC38A3 is required for the regulation and maintenance of cellular GSH levels and GSH/GSSG ratio in breast cancer." (PMID 38785550, 2024). "Even though SLC38A3 exhibits functional features that are almost identical with those of SLC38A5, the expression of the former is actually decreased in breast cancer, and the decrease is independent of the hormone receptor status of the tumor (TCGA database)." (PMID 34704597, 2021).
developmental delay (3 papers, 2022 to 2023). "For example, mutations in Slc38a3 cause overall developmental delay, intellectual disability, hypotonia, and loss of speech, Adamts5 prevents impaired cardiac function by regulating versican degradation, and Cdkn2a/b locus influences the risk of diabetes through both islet and non-islet mechanisms." (PMID 37305038, 2023). "The impact of glutamine cycling on brain function has been highlighted by the recent discovery of rare biallelic variants in SLC38A3, resulting in global developmental delay, microcephaly, epilepsy, absent speech and visual impairment." (PMID 36139028, 2022). "Patients with SLC38A3 variants mainly present with axial hypotonia, absent speech, global developmental delay/mental retardation, epilepsy, and visual impairment." (PMID 36419532, 2022).
Hyperammonemia (3 papers, 2019 to 2022). An increased concentration of ammonia in the blood. "This review focuses on the effects of hyperammonemia on the two glutamine carriers located in the astrocytic membrane: Slc38a3 (SN1, SNAT3) and Slc7a6 (y + LAT2)." (PMID 35733937, 2022).
Anxiety (2 papers, 2018 to 2026). Intense feelings of nervousness, tension, or panic often arise in response to interpersonal stresses. "Slc38a3 and Gng4 expression were altered in EFhd2 knockout mouse associated with anxiety and alcohol addiction." (PMID 29391390, 2018).
diabetes (2 papers, 2022 to 2023). "SLC38A3 induction mediates glutamine transport in β-cells of pancreas, and its downregulation was found in islets of diabetes-prone db/db mice." (PMID 36364703, 2022).
Obesity (2 papers, 2022). Accumulation of substantial excess body fat. "In the present review, we highlight the unusual involvement of selective amino acid transporters in macropinocytosis (SLC38A5/SLC38A3) and diet-induced obesity/metabolic syndrome (SLC6A19/SLC6A14/SLC6A6)." (PMID 35204736, 2022). "Five differentially methylated regions were in genes previously found to be associated with obesity and altered metabolic states (TRAP1, SLC38A3, PROX1, ALDH1B1, and FAM96A)." (PMID 36474183, 2022). "Of these genes, four (TRAP1, SLC38A3, PROX1, and FAM96A) have also been associated with obesity and altered metabolic states, indicating that they may be implicated in differential progression of lean versus obese NASH-HCC." (PMID 36474183, 2022).
cyst (1 paper, 2023). A sac-like closed membranous structure that may be empty or contain fluid or amorphous material. "During the early stages of cyst progression via high protein load, kidney epithelial cells upregulate expression of gluconeogenesis marker Pepck1, chloride channel Clcnka, and sodium-coupled glutamine transporter Slc38a3, prior to the rise in kidney MФs." (PMID 37538309, 2023).
esophageal squamous cell carcinoma (1 paper, 2024). Esophageal squamous cell carcinoma (ESCC) is a type of esophageal carcinoma (EC) that can affect any part of the esophagus, but is usually located in the upper or middle third. "Also, in esophageal squamous cell carcinoma, copy number alterations have been found to be the leading cause of SLC38A3 downregulation, which in turn was associated with increased epithelial-to-mesenchymal transition and tumor aggressiveness." (PMID 39062801, 2024).
Hypoglycemia (1 paper, 2019). A decreased concentration of glucose in the blood. "SLC38A3 expression linked with tissue development is demonstrated by short life of SLC38A3 mutant mice with hypoglycemia, suggesting that glutamine transport is crucial for growth and development." (PMID 30239845, 2019).
lung carcinoma (1 paper, 2015). "The Oligo GRN hubgene CYP4A11 was shown to promote angiogenesis and metastasis in lung cancer and SLC38A3 (SNAT3) is a glutamine transporter and has been described as a marker for malignant glioma." (PMID 25971253, 2015).
meningioma (1 paper, 2016). A generally slow growing tumor attached to the dura mater. "Autosomal genes that were comparably lower expressed in meningiomas from females included EPH receptor A3 (EPHA3), parvalbumin (PVALB), calbindin 2 (CALB2), and solute carrier family 38 member 3 (SLC38A3)." (PMID 27096627, 2016).
tumor (12 papers, 2015 to 2025). "Upregulated genes included cartilage-associated genes (COMP, MATN3, and COL11A2), collagen- and extracellular matrix-associated genes (COL9A2, SFRP2, and SERPINE2), and tumor metastasis- and progression-associated genes (SLC38A3, FST, ITGA11, and DGKI)." (PMID 36192442, 2022). "Functional experiments suggested that SLC38A3 overexpression promotes epithelial-mesenchymal transition and accelerates tumor metastasis by regulating glutamine and histidine transport." (PMID 34977043, 2021). "For example, upregulation of the solute carrier, solute carrier family 38 member 3 (SLC38A3), has been shown in metastatic tumor cells." (PMID 31027222, 2019). "Conversely to SLC38A3, upregulation of SLC38A1, SLC7A6, and SLC1A5 transporters in HCC tumors was associated with decreased overall patient survival, with SLC1A5 being the most significantly associated with tumor aggressiveness." (PMID 39062801, 2024). "Subsequently, the results of RT-qPCR experiments demonstrated that the mRNA expression levels of SLC38A2, SLC38A3 and SLC38A4 were significantly overexpressed in GC tumor tissues." (PMID 36918802, 2023).
cancer (10 papers, 2016 to 2025). A tumor composed of atypical neoplastic, often pleomorphic cells that invade other tissues. "As dedifferentiation of cancer cells is globally accepted to be a hallmark of advanced malignant tumors, this supports the idea that the loss of SLC38A3 is associated with more aggressive HCC behavior." (PMID 39062801, 2024). "Given this possible protective role against tumorigenesis and cancer progression, loss of SLC38A3 expression might represent a pro-tumorigenic mechanism, in addition to reflecting the dedifferentiation process that inevitably occurs during HCC tumorigenesis." (PMID 39062801, 2024). "Five hypermethylated regions were in genes previously associated with cancer (TRAP1, SLC38A3, CHRM1, EDN2, and PROX1), while six hypomethylated regions were in genes previously associated with cancer (NUMBL, ALDH1B1, FTCD, FASTKD2, FAM96A, and ARHGAP15)." (PMID 36474183, 2022). "Comparing HCC in the choline deficient model and choline supplemented model, significant methylation differences were seen in 11 genes previously associated with cancer (hypermethylation of TRAP1, SLC38A3, CHRM1, EDN2, and PROX1; hypomethylation of ALDH1B1, FTCD, FASTKD2, FAM96A, and ARHGAP15)." (PMID 36474183, 2022). "The SLC38A3 (SNAT3) gene is known to be overexpressed in cases of triple-negative BC and has been shown to promote cancer cell invasion and metastasis through the SLC38A3/GLULK3β/β-linker protein/EMT pathway." (PMID 40598593, 2025). "Several SLC38 isoforms have previously been linked to cell proliferation, invasion, migration and/or angiogenesis, including SLC38A2, SLC38A3, SLC38A6 and SLC38A7, supporting their involvement in cancer progression." (PMID 38254895, 2024). "SLC6A14 (ATB0,+) that broadly accepts large neutral amino acids, as well as SLC38A2 (SNAT2), SLC38A3 (SNAT3) and SLC38A7 (SNAT7) that accept some large neutral amino acids such as His, Met and Leu are known to be upregulated in certain types of cancers." (PMID 36071551, 2022).
nervous system diseases (1 paper, 2022). "SGK3 can up-regulate GluR1, GluR6, EAAT1, EAAT2, EAAT4, EAAT5, and SLC38A3, participate in the transport of glutamate and glutamine in the nervous system, and play a role in (pathological) physiological process of various nervous system diseases." (PMID 36531961, 2022).
SLC38A3 also shares sentences with these, for which no sentence is quoted: infection (3 papers); Acidosis (2); Cognitive impairment (2); depression (2); epilepsy (2); non-small cell lung carcinoma (2); Ataxia (1); cervical cancer (1); cleft lip (1); colorectal cancer (1); complication (1); Crohn disease (1); Epileptic encephalopathy (1); glioblastoma (1); Hepatic steatosis (1); hepatoma (1); Hypertension (1); influenza (1); Insulin resistance (1); Intellectual disability (1); keloid (1); malignant glioma (1); metabolic acidosis (1); metabolic syndrome (1); microcephaly (1); neuroblastoma (1); Type 2 Diabetes (1).